B3GAT2 (beta-1,3-glucuronyltransferase 2)
Description:
Involved in the biosynthesis of L2/HNK-1 carbohydrate epitope on both glycolipids and glycoproteins.
Synonyms: GlcAT-S; GLCATS
Tractability: Small molecule: it has a binding pocket of medium quality. Antibody: UniProt predicts a signal peptide or a membrane-spanning region. PROTAC: its protein half-life has been measured.
Gene: Protein-coding gene on chromosome 6 (70,856,679 to 70,957,060, reverse strand). Ensembl gene ENSG00000112309.
Subcellular location: Golgi apparatus membrane
Pathways (Reactome):
Metabolism: Glycosaminoglycan-protein linkage region biosynthesis
Gene Ontology:
Molecular function: galactosylgalactosylxylosylprotein 3-beta-glucuronosyltransferase activity
Biological process: chondroitin sulfate proteoglycan biosynthetic process; carbohydrate biosynthetic process
Cellular component: Golgi membrane; Golgi apparatus; membrane
Genetic constraint (gnomAD): Loss-of-function variants: 26 observed, 26.52 expected, observed/expected ratio (o/e) 0.98, 90% interval 0.72 to 1.36. The synonymous counts are far from expectation, so gnomAD's model fits this gene poorly and the ratio says little. Missense variants: 458 observed, 420.94 expected, observed/expected ratio (o/e) 1.09, 90% interval 1.01 to 1.17. Synonymous variants: 218 observed, 173.73 expected, observed/expected ratio (o/e) 1.25, 90% interval 1.12 to 1.4.
Homologues: Orthologues: dog B3GAT2 (96% identical), rabbit B3GAT2 (95% identical), pig B3GAT2 (94% identical), chimpanzee B3GAT2 (92% identical), macaque B3GAT2 (91% identical), mouse B3gat2 (91% identical), rat B3gat2 (90% identical), tropical clawed frog b3gat2 (76% identical), zebrafish b3gat2 (68% identical), Caenorhabditis elegans glct-5 (31% identical), Caenorhabditis elegans glct-4 (30% identical), Caenorhabditis elegans glct-6 (30% identical), and 3 more. Paralogues in human: B3GAT1 (51% identical), B3GAT3 (45% identical).
Diseases named in the same sentence as B3GAT2 in open-access papers:
B3GAT2 is named in the same sentence as 33 diseases in open-access papers, as found by Europe PMC text mining. Sharing a sentence is not in itself a finding about the gene and the disease. The quoted sentences say what the papers report.
colorectal cancer (4 papers, 2011 to 2022). A primary or metastatic malignant neoplasm that affects the colon or rectum. "B3GAT2 is hypermethylated in lung cancer and colorectal cancer, and its hypermethylation has been used in colorectal cancer diagnosis." (PMID 33747079, 2021). "Methylation of B3GAT2, a member of the panel as biomarker, has been used for diagnosis in colorectal cancer." (PMID 30867848, 2019).
depression (1 paper, 2014). "B3GAT1 is near a balanced translocation that segregates in a family with psychosis and depression, and an association to B3GAT2 has been found in SZ." (PMID 24736721, 2014).
endometrial cancer (1 paper, 2021). Primary or metastatic malignant neoplasm involving the endometrium (mucous membrane that lines the endometrial cavity). "The results of Kaplan–Meier prognostic analysis showed that high expression of the risk-associated genes (B3GAT2, CD3EAP, FRMPD3, LINC01224, LINC02068, LY6H, and NR6A1) is related to poor prognosis in endometrial cancer patients (P < 0.05)." (PMID 33747079, 2021).
tumor (3 papers, 2016 to 2022). "CIMP status was predicted using an established array-based marker panel of CIMP, including B3GAT2, FOXL2, KCNK13, RAB31, and SLIT1, that was shown to identify CIMP+ (CIMP-H or CIMP-L) tumours with 100% sensitivity and 95.5% specificity, with 2.4% misclassification." (PMID 27846243, 2016).
psychiatric disorder (1 paper, 2016). A disorder characterized by behavioral and/or psychological abnormalities, often accompanied by physical symptoms. "It is noted that 7 genes, DAO, PRDX6, KCNN3, TCF7L2, RFX4, FYN, and B3GAT2 (yellow-colored nodes), relevant to psychiatric disorders are involved and interestingly these genes except B3GAT2 constitute a connected subgraph." (PMID 27510319, 2016).
B3GAT2 also shares sentences with these, for which no sentence is quoted: cancer (7 papers); breast carcinoma (2); diabetes (2); lung carcinoma (2); melanoma (2); prostate carcinoma (2); allergic rhinitis (1); Barrett’s oesophagus (1); carcinoids (1); colitis (1); colon cancer (1); esophageal cancer (1); gastrointestinal carcinomas (1); gastrointestinal disorders (1); Hepatic fibrosis (1); hepatocellular carcinoma (1); infection (1); inflammatory bowel disease (1); invasive breast carcinoma (1); lung adenocarcinoma (1); metabolic disorders (1); neutropenia (1); Obesity (1); prostate adenocarcinoma (1); psychosis (1); sarcoma (1); steatosis (1); synovial sarcoma (1).